ZFP64 (ZFP64 zinc finger protein)
Description:
May be involved in the regulation of mesenchymal cell differentiation through transactivation of NOTCH1 target genes.
Synonyms: ZNF338; FLJ10734; dJ831D17.1; FLJ12628; dJ548G19.1
Tractability: PROTAC: UniProt records ubiquitination sites on it.
Gene: Protein-coding gene on chromosome 20 (52,051,663 to 52,204,308, reverse strand). Ensembl gene ENSG00000020256.
Subcellular location: Nucleus
Subcellular location (Human Protein Atlas): Nucleoplasm
Gene Ontology:
Molecular function: protein binding; DNA-binding transcription factor activity; transcription cis-regulatory region binding
Biological process: mesenchymal cell differentiation; regulation of DNA-templated transcription
Cellular component: cytoplasm; megasporocyte nucleus; nucleus
Genetic constraint (gnomAD): Loss-of-function variants: 15 observed, 52.96 expected, observed/expected ratio (o/e) 0.28, 90% interval 0.19 to 0.44. The upper end of that interval is the gene's LOEUF score, 0.44, which puts it in group 1 of 6, group 1 being the genes least tolerant of losing a copy. Missense variants: 754 observed, 918.65 expected, observed/expected ratio (o/e) 0.82, 90% interval 0.77 to 0.87. Synonymous variants: 375 observed, 368.27 expected, observed/expected ratio (o/e) 1.02, 90% interval 0.94 to 1.11.
Homologues: Orthologues: chimpanzee ZFP64 (99% identical), macaque ZFP64 (99% identical), dog ZFP64 (96% identical), pig ZFP64 (96% identical), guinea pig ZFP64 (92% identical), rat Zfp93 (88% identical), tropical clawed frog zfp64 (53% identical), mouse Zfp64 (51% identical), zebrafish zfp64 (41% identical), Drosophila melanogaster CG9932 (20% identical), Drosophila melanogaster CG4707 (15% identical), Drosophila melanogaster CG4282 (15% identical), and 6 more. Paralogues in human: ZNF335 (22% identical).
Diseases named in the same sentence as ZFP64 in open-access papers:
ZFP64 is named in the same sentence as 14 diseases in open-access papers, as found by Europe PMC text mining. Sharing a sentence is not in itself a finding about the gene and the disease. The quoted sentences say what the papers report.
gastric cancer (4 papers, 2022 to 2024). A primary or metastatic malignant neoplasm involving the stomach. "Zinc mainly contributes to gastric cancer cell resistance through zinc finger proteins such as ZFP64, GLI1, ZFP91, ZNF139, which regulate gastric cancer cell resistance through pathways such as GAL-1, MALAT1, AKT-mTOR, or by modulating miRNA." (PMID 38370477, 2024). "ZFP64 was significantly upregulated in various types of human cancers, including gastric cancer (GC), hepatocellular carcinoma (HCC), and oesophageal cancer." (PMID 37760477, 2023). "Given that stemness-like activation often contributes chemoresistance in cancer, we hypothesized that ZFP64 may also promote gastric cancer stemness." (PMID 34996504, 2022). "Furthermore, three genes that we found to be amplified in serum-treated HEK293T cells (i.e., AURKA, RAE1, and ZFP64) are known to increase the resistance of pancreatic, colorectal, and gastric cancer cells to paclitaxel." (PMID 36289850, 2022). "The ZFP64/GAL-1 axis promotes the therapeutic effect of nab-paclitaxel and counteracts the immunosuppressive microenvironment in gastric cancer." (PMID 38370477, 2024).
hepatocellular carcinoma (4 papers, 2015 to 2023). A malignant tumor that arises from hepatocytes. "Interestingly, when resminostat (1 μmol/l) was added subsequent to infections with MeV-SCD (employing adjusted MOIs), again lower zfp64 mRNA expression levels were observed in all three hepatoma cell lines when being compared to untreated controls (purple bars)." (PMID 27119111, 2015). "When resminostat (1 μmol/l) was applied alone (i.e., in absence of MeV-SCD), it was found to inhibit zfp64 mRNA production quite effectively in all three human hepatoma cell lines at early time points, i.e., at 5 hours after addition of resminostat (blue bars)." (PMID 27119111, 2015). "Similarly, in hepatocellular carcinoma (HCC) patients, a high expression of PKCα has been reported to stimulate the M2-like polarization of macrophages, accompanied by immune escape and a lack of response to the anti-PD1 blockade by promoting the nuclear import of ZFP64." (PMID 37626933, 2023).
leukemia (3 papers, 2020 to 2023). A malignant (clonal) hematologic disorder, involving hematopoietic stem cells and characterized by the presence of primitive or atypical myeloid or lymphoid cells in the bone marrow and the blood. "Recently, ZFP64 was identified to be a crucial TF in MLL-rearranged leukemia by controlling the expression of the oncogene MLL, prompting the formal proposal that ZFP64 was an important TF in cancer progression." (PMID 34996504, 2022). "ZFP64 was shown as required for MLL-r leukemia survival in a project of domain-focused CRISPR/Cas9 screens that target 1426 DNA-binding domains (total 8658 sgRNAs) over 33 cancer cell lines." (PMID 32806592, 2020). "A recent study identified a critical role for ZFP64 as a TF (transcriptional factor) with an important role in maintaining the expression of the MLL oncogene in MLL (mixed lineage leukemia gene-rearranged leukemia)." (PMID 34996504, 2022). "Additionally, ZFP64 directly promotes the expression of MLL in human leukemia." (PMID 36918927, 2023).
lymph node metastasis (2 papers, 2022 to 2023). "Combined with clinical parameters, we found high ZFP64 expression significant correlated with lymph node metastasis (P < 0.001), a large tumor size (P < 0.001), pTNM stage (P < 0.001) and thrombus in vessels encapsulating the tumor (P < 0.001)." (PMID 34996504, 2022). "Patients with high expression level of ZFP64 showed higher rates of lymph node metastasis, liver invasion, nerve invasion, and lower tumor differentiation, which might also be related to the facilitative effect of ZFP64 on the migration and invasion of GBC cells." (PMID 37760477, 2023).
breast carcinoma (1 paper, 2025). "Histone lactylation (e.g., H3K18la) drives pro-tumorigenic gene programs, such as PDGFA upregulation in macrophages and ZFP64-mediated chemoresistance in breast cancer." (PMID 40565047, 2025). "CAFs-derived lactic acid regulates iron death by enhancing histone H3K18la lactylation of ZFP64, which promotes drug resistance in breast cancer cells." (PMID 40565047, 2025).
esophageal cancer (1 paper, 2024). A primary or metastatic malignant neoplasm involving the esophagus. "Zinc finger protein 64 (ZFP64) is a transcription factor for cytotoxic T-lymphocyte-associated protein 4 (CTLA-4) and anti- PD-1 in esophageal cancer." (PMID 38915413, 2024).
gallbladder carcinoma (1 paper, 2023). "In 50 gallbladder carcinoma tissues, the mRNA levels of ZFP64 in metastatic gallbladder carcinoma tissues were higher than that in non-metastatic gallbladder carcinoma tissues." (PMID 37760477, 2023). "We found that ZFP64 expressed higher in GBC gallbladder carcinoma tissues than in normal tissues and was positively correlated with poor prognosis." (PMID 37760477, 2023). "In summary, ZFP64 promotes the progression of gallbladder cancer through activating the Notch1 signaling pathway." (PMID 37760477, 2023). "Similarly, Western blot analysis showed the analogous results in protein levels: the expression of ZFP64 was significantly higher in gallbladder carcinoma tissues than in adjacent normal tissues in all 10 GBC patient samples." (PMID 37760477, 2023). "Indeed, the RT-qPCR results showed that ZFP64 mRNA levels were evidently much higher in gallbladder carcinoma tissues than in adjacent normal tissues from GBC patients." (PMID 37760477, 2023). "Therefore, ZFP64 could promote gallbladder cancer growth in vivo." (PMID 37760477, 2023). "Through the RT-qPCR and the western blot assays, we demonstrated that ZFP64 expressed evidently higher in gallbladder carcinoma tissues from GBC patients than in normal tissues, and that GBC patients with high ZFP64 expression appeared to have an extremely worse prognosis." (PMID 37760477, 2023).
lung adenocarcinoma (1 paper, 2024). A carcinoma that arises from the lung and is characterized by the presence of malignant glandular epithelial cells. "Overexpression of ZFP64 promotes the proliferation of lung adenocarcinoma cells through activating the Notch pathway and is associated with poor prognosis." (PMID 39185313, 2024).
Sepsis (1 paper, 2022). Sepsis is defined as life-threatening organ dysfunction caused by a dysregulated host response to infection. "While the transcription factor Zinc Finger Protein 64 (ZFP64) has been explored in cancer metastasis, its role in sepsis has not been fully defined." (PMID 35634310, 2022).
tumor (6 papers, 2021 to 2024). "Nab-paclitaxel treatment elicited potent inhibition of tumor growth; however, the growth inhibition caused by nab-paclitaxel was diminished in ZFP64-overexpressing tumors." (PMID 34996504, 2022). "The studies have discovered the upregulation of zinc finger protein 64 (ZFP64) in tumor tissues of patients with HCC resistance to anti-PD1 therapy." (PMID 38997696, 2024). "Using RNA-seq and ChIP-seq analyses, we found that elevated ZFP64 expression conferred a stem cell-like phenotype to tumor cells and promoted immunosuppression in the tumor via the transcriptional activation of GAL-1 in GC." (PMID 34996504, 2022). "Our data support a pivotal role for ZFP64 in GC progression by simultaneously promoting cellular chemotherapy resistance and tumor immunosuppression." (PMID 34996504, 2022). "Here, we further established a coculture system of peripheral blood mononuclear cells (PBMCs) and tumor cells with different levels of ZFP64 expression." (PMID 34996504, 2022). "Given the clinical evidence suggesting a potential role for ZFP64 in tumor metastasis, we sought to experimentally confirm this possibility." (PMID 34996504, 2022). "Thus, we identified a pivotal role for ZFP64 in GC progression by simultaneously promoting cellular drug resistance and tumor immunosuppression and revealed a novel mechanism of GC chemoresistance." (PMID 34996504, 2022). "Based on the dysregulation of several oncogenic and tumor suppressor genes that directly regulate immune checkpoint expression and result in immunosuppression, ZFP64 might also be a bona fide driver of GC and a direct regulator of the tumor immune microenvironment in GC." (PMID 34996504, 2022). "Indeed, several high-throughput genomic and proteomic analyses revealed that ZFP64 was upregulated in tumor tissues compared to the corresponding paracancerous tissues and might be a novel potential oncogene." (PMID 34996504, 2022). "The analysis revealed that patients with high expression of ZFP64 had higher CA19-9 levels and higher rates of lymph node metastasis, liver invasion, nerve invasion, and lower tumor differentiation." (PMID 37760477, 2023). "Considering the involvement of ZFP64 in the microenvironment, we further compared HGC27 tumor growth in humanized mice treated with nab-paclitaxel monotherapy or combination therapy." (PMID 34996504, 2022). "ZFP64 functions as a transcription factor that promotes the expression of Galectin-1 (GAL-1), contributing to stem-cell-like properties and an immunosuppressive tumor environment." (PMID 39185313, 2024). "Based on the ChIP-seq and promoter luciferase activity analyses, ZFP64 activated Gal-1 transcription by binding to the Gal-1 promoter, which induced cellular acquisition of the CSC phenotype and established an immunosuppressive tumor microenvironment." (PMID 34996504, 2022).
cancer (3 papers, 2022 to 2025). A tumor composed of atypical neoplastic, often pleomorphic cells that invade other tissues. "Cancer-associated fibroblasts (CAFs) confer doxorubicin resistance to TNBC by augmenting zinc finger protein 64 (ZFP64)-mediated histone lactylation, thereby modulating ferroptosis sensitivity." (PMID 41502519, 2025).
infection (2 papers, 2023 to 2025). The state of being infected such as from the introduction of a foreign agent such as serum, vaccine, antigenic substance or organism. "Since these upregulated genes function in cells other than PCs, the ZFP64-KD in PCs must have upregulated their expression indirectly or through a leaky infection of ZFP64-KD lentivirus to GCs (See limitations of the study)." (PMID 40546958, 2025). "To further elucidate the specific biological functions of ZFP64 in GBC progression, we generated GBC-SD and NOZ cell lines with stable overexpression or the knockdown of ZFP64 via lentivirus-mediated infection." (PMID 37760477, 2023).
ZFP64 also shares sentences with these, for which no sentence is quoted: colorectal adenoma (1 paper); colorectal carcinoma (1).